EGFR (epidermal growth factor receptor)
Diseases named in the same sentence as EGFR in open-access papers (continued):
Sharing a sentence is not in itself a finding about the gene and the disease.
lung cancer (continued). "Bruceine H, a derivative of Brucea javanica (L.), was found to overcome resistance to receptor tyrosine kinase (RTK)‐EGFRi in non‐small cell lung cancer (NSCLC) models by suppressing Notch3, EGFR activation and β‐catenin expression., thereby increasing gefitinib response." (PMID 37697969, 2023). "Using transcriptome data, we found genes for 16 of these proteins which were expressed specifically in EGFR mutant LUAD, suggesting they may be biomarker candidates for this molecular subtype of lung cancer." (PMID 38260835, 2023). "Regardless of the EGFR type, 8PN reduced the viability of lung cancer cells in a dose‐dependent manner after 3 days of treatment, with IC50 values ranging from 22 to 100 μm, whereas it had no cytotoxicity in mouse splenocytes." (PMID 37013960, 2023). "Theoretically, EGFR inhibition disfavors ferroptosis because MAPK signaling is required for ferroptosis, while its inhibition by EGFR or ERK inhibitors aborts the process of ferroptosis in lung cancer cells." (PMID 36864513, 2023). "Studies have shown that normal doses or high doses of EGFR-TKI and ALK-TKI can alter the immune microenvironment in lung cancer, but whether immune activation or immune suppression occurs needs to be further explored." (PMID 37901223, 2023). "Epidermal growth factor receptor (EGFR) directly binds to SCD1 and phosphorylates its Tyr55 residue, which maintains the stability of SCD1 protein and increases MUFA levels to facilitate lung cancer growth." (PMID 37240297, 2023). "Previous studies have proved that YAP1 promotes survival and dormancy without EGFR downstream signaling in EGFR-mutant lung cancer." (PMID 37215986, 2023). "Many trials supported pembrolizumab as a first-line monotherapy to significantly improve overall survival (OS) in selected patients with previously untreated metastatic Non–Small Cell Lung Cancer (mNSCLC) and a PD-L1 TPS of ≥50% without EGFR/ALK mutations." (PMID 37189193, 2023). "In lung cancer 27, TSLNC8 overexpression led to smaller tumor volume and weight, reduced expression of EGFR, p-EGFR, and p-STAT3 levels, and combination with osimertinib administration effectively suppressed tumor growth, enhancing osimertinib's anti-tumor effects." (PMID 37781073, 2023). "Very recently, targeting both EGFR and VEGFR1 by a bispecific decoy receptor, able to capture both EGF-like and VEGF ligands, showed great anti-tumor activity in a preclinical in vivo model of lung carcinoma." (PMID 37041632, 2023). "EGFR activity was required for mucin expression in lung carcinoma cells treated with A. fumigatus extract, but no increase in the level of phosphorylated EGFR was observed." (PMID 37357550, 2023). "EGFR is expressed in various cancers, including, but not limited to, lung carcinoma, rectal/colon cancer, melanoma and squamous cell carcinoma." (PMID 38067344, 2023). "EGFR amplification was identified in 22% of KDD cases and was not restricted to lung cancer and EGFR KDD." (PMID 36325957, 2023). "None of the 1293 lung carcinomas with driver alterations in EGFR/ALK/ROS1/RET/MET oncogenes had NTRK 5′/3′-end expression imbalances." (PMID 37762506, 2023). "Likewise, lupeol induced apoptosis by inhibiting EGFR phosphorylation and dephosphorylation of its downstream molecule, STAT3, in lung cancer cells (H1299, A549 and H460)." (PMID 35267408, 2022). "Top-down approaches are exemplified by the discovery of NRF2 activations, which were detected in all lung cancer tissues regardless of the status of other biomarkers, such as EGFR, ALK, ROS-1 and other genetic alterations." (PMID 35806042, 2022). "EGFR is highly expressed in a variety of malignant tumors, and its receptor dimerization can activate JAK1 and STAT, thereby regulating the cell cycle and apoptosis of lung cancer cells." (PMID 35190747, 2022). "In patients with lung cancer harboring fusion transcripts of BCAR4, no other known activating mutations of EGFR and KRAS genes were found." (PMID 36081848, 2022).
lung cancer (continued). "While somatic mutations of EGFR, BRAF, HER2, MET and chromosomal rearrangements of ALK, ROS1, RET are responsible for lung cancer, risk factors for these genomic alterations have not yet been identified." (PMID 36208308, 2022). "Gefitinib, an epidermal growth factor receptor-tyrosine kinase inhibitor (EGFR-TKI),is the currently recommended first-line therapy for advanced EGFR-mutant lung cancer, and understanding the mechanism of resistance is the key to formulating therapeutic strategies for EGFR-TKIs." (PMID 36471952, 2022). "Two studies in lung cancers showed that a low expression of BIM, a member of the BCL-2 family, in treatment-naïve patients prevents the induction of apoptosis and mediates an intrinsic resistance to EGFR-TKI." (PMID 35681591, 2022). "There are no consistent results regarding the predictive value of EGFR serum levels in lung cancer patients and, more importantly, its ability to predict therapeutic response to anti-EGFR drugs." (PMID 35053080, 2022). "A first-generation EGFR-TKI, gefitinib, was efficacious in patients with EGFR-positive lung cancer and poor PS, but the clinical utility and safety of osimertinib, a third-generation EGFR-TKI, remain unclear." (PMID 34643820, 2022). "In vivo studies reveal that ablation of DARPP-32 protein activity sensitizes gefitinib-resistant lung tumor xenografts to EGFR TKI treatment, while DARPP-32 overexpression increases gefitinib-refractory lung cancer progression in gefitinib-sensitive lung tumors orthotopically xenografted into mice." (PMID 34675407, 2022). "Crosstalk between EGFR and c-MET in lung cancer has been widely reported." (PMID 35069735, 2022). "On the other hand, the prevalence of ErbB family gene fusions in our lung cancer cohort was non-negligible reaching 0.23%, with the majority of these patients carrying EGFR (0.11%) and ERBB2 (0.07%) fusions." (PMID 36369474, 2022). "CD44 expression may play a significant role in epidermal growth factor receptor (EGFR)-mutant neoplasms, particularly in early NSCLC, and CD44 is important in predicting EMT upon EGFR-TKI monotherapy in patients with lung cancer." (PMID 35719973, 2022). "Furthermore, researchers reported that KIF22 can influence the biological processes of phosphorylation for epidermal growth factor receptor (EGFR), which can weaken EGFR internalization and promote EGF-dependent lung cancer cell proliferation." (PMID 35578724, 2022). "In this study, we found that high eosinophil count, history of EGFR-TKI targeted therapy, cycles of ICI administration, and lung cancer were significantly correlated with the incidence of irAEs (p < 0.005), and cycles of ICI administration and lung cancer were independent risk factors for irAEs." (PMID 36438818, 2022). "Moreover, functional experiments have shown that EGFR inhibitor sensitivity is directly related to increased ECAD expression in colon cancer and in lung cancer." (PMID 34890102, 2022). "In order to investigate how GYP exerts its anti-LC effects by regulating metabolites and metabolic pathways as well as enhancing the anti-lung cancer effects of chemotherapeutic agents, the relative contents of STAT3, EGFR, MAPK14, and TYMS between the six groups were analyzed by western blot." (PMID 36532716, 2022). "To do so, we tested the obtained compounds against the human lung cancer cells, including EGFR-mutant and non-mutant cell lines." (PMID 35203671, 2022). "Since patients who developed EGFR mutant lung adenocarcinomas with acquired resistance to EGFR inhibitor drugs (gefitinib or erlotinib) exhibit increased copy numbers of MET, c-Met-HGF inhibitors are used for lung cancer treatment alone or in combination with other drugs." (PMID 35986321, 2022). "The combined treatment with Se and radiation is more effective and results in the markedly improved inhibition of EGFR expression in human lung cancer cells (NCI-H460 and H1299) without EGFR mutation than in the treatment with radiation alone." (PMID 36547898, 2022).
lung cancer (continued). "We showed that inhibition of EGFR by gefitinib reduced hypoxia-induced HIF-1α expression, compatible with the previous report showing a decrease in hypoxia-induced accumulation of HIF-1α after EGFR inhibition in human lung cancer A549 cells." (PMID 35634326, 2022). "AR is expressed in several types of lung cancer, including small cell, adenocarcinoma, and squamous cell carcinoma, and dihydrotestosterone (DHT) induces a proliferative response in lung cancer cells through cross‐talk of AR and EGFR." (PMID 33350105, 2022). "EGFR S645C continuously activates downstream signaling including Erk1/2 and MEK inhibitor can partly counter the resistance induced by EGFR S645C in lung cancer." (PMID 35814475, 2022). "The logistic regression model combining the five mRNA biomarkers (CCNI, EGFR, FGF19, FRS2, and GREB1) can distinguish patients with lung cancer from normal controls (area under the receiver operating characteristic curve [AUC-ROC] = 0.925; sensitivity = 93.75%; specificity = 82.81%)." (PMID 35651679, 2022). "Recently, we have developed and reported a non-covalent imidazo[1,2-a]quinoxaline-based EGFR inhibitor (6b), which showed promising inhibitory activity against the gefitinib-resistant H1975(L858R/T790M) lung cancer cell line." (PMID 36080307, 2022). "In this case study, we report that treatments with olaparib, a Poly (ADP-ribose) polymerase (PARP) inhibitor, combined with dacomitinib, a second-generation EGFR TKI, benefited a lung cancer patient with osimertinib-resistant brain and leptomeningeal metastases." (PMID 35494030, 2022). "To assess whether RBM10 expression could modulate apoptosis in EGFR-mutant lung cancer, we first assessed cleavage of the apoptotic biomarker poly (ADP-ribose) polymerase (PARP) in H3255 (EGFR L858R/RBM10 WT) and PC-9 (EGFR del19/RBM10 WT) cells." (PMID 35579943, 2022). "In nonsmall cell lung cancer cells, reduced CEMIP suppresses proliferation and migration of nonsmall cell lung cancer cells and down-regulated the expression of several transcription factors related to the EMT process and EGFR signaling." (PMID 36451490, 2022). "In lung cancer, CB2 activation suppressed EMT and tumor progression by downregulating EGFR." (PMID 35641479, 2022). "The EGFR wild type and KRAS mutant Lewis lung carcinoma (LLC1)-bearing mouse is widely used as a model for testing the molecular mechanisms, anti-metastatic activity, and immunity of anticancer agents, although it is not an EGFR-mutant lung cancer model." (PMID 36547898, 2022). "In addition to chemotherapeutic drugs and EGFR-TKI inhibitors, the combination of STAT3 inhibitors and other small molecular inhibitors has also achieved promising therapeutic effects on lung cancer." (PMID 36559280, 2022). "In keeping with published clinical trial and meta-analysis data, these data suggest that we need to monitor the incidence of irAEs frequently for the people who have received EGFR-TKI therapy and are later receive ICIs treatment, especially the people with lung cancer." (PMID 36438818, 2022). "In lung cancer, RYK promotes resistance acquired upon EGFR inhibition." (PMID 36471440, 2022). "In addition, we provided a function of LEPRE1 as a new biomarker and its novel mechanism for EGFR-TKI drug responsiveness in various AML-derived and lung cancer-derived cells." (PMID 35190588, 2022). "Consistent with prior studies, patients with EGFR-mut lung cancer were far more likely to be female and non-smokers than in the other cohorts." (PMID 36612014, 2022). "As HMGA1 is an upstream negative regulator of the EGFR signaling pathway, it could be speculated that gender-specific HMGA1 expression influences lung cancer cell behavior." (PMID 35805937, 2022).
lung cancer (continued). "NAC was previously found to restore the sensitivity of gefitinib-resistant lung cancer cells to gefitinib that is a major epithelial growth factor receptor tyrosine kinase inhibitor, suggesting the inhibitory effects of NAC on EGFR activation in epithelial cells." (PMID 36046596, 2022). "EGFR has been detected in exosomes from cell culture supernatants of five human cancer cell lines (HARA, HARA-B, A549, RERF-LC-MS, and LU65), the plasma of HARA-B tumor-bearing mice, and the plasma of human lung cancer patients." (PMID 35158999, 2022). "ND-Cet treatment increased cellular uptake ability of nanocomposites in the EGFR-expressed cells but not in the EGFR-negative lung cancer cells." (PMID 36678740, 2022). "CXCL10 (dot #4) was elevated in coculture supernatants derived from all the EGFR-mutant lung cancer lines (HCC4006, HCC827, and H1975) and did not decrease after EGFR-TKI treatment." (PMID 36612121, 2022). "However, it was reported that arecoline, an alkaloid with muscarinic and nicotinic effects, induced migration and activation of EGFR, with further cascade activation involving c-Src and FAK signaling in the A549 lung cancer cell line." (PMID 35565451, 2022). "However, epidemiologic data show that up to 25% of lung cancers can develop in nonsmokers; in these patients, the development of cancer has been linked with specific driver genetic alterations, with the epidermal growth factor receptor (EGFR) gene being the most common globally." (PMID 35884398, 2022). "We found that co-treatment with MA and osimertinib in lung cancer cells significantly inhibited the expression of FTH1 compared with the osimertinib alone treatment group, which further activated the ferroptosis pathway and enhanced EGFR-TKI sensitivity." (PMID 36712673, 2022). "Interestingly, our results showed that the risk of VTE in ROS1 rearrangements(ROS1+) patients is 2.63-fold greater than that in ROS1- patients, and the odds of VTE in ROS1+ lung cancer were higher than ALK+, EGFR+ and KRAS+ cohorts in the univariate analysis." (PMID 36300098, 2022). "Therefore, potential EGFR-TKI sensitizers and treatment strategies to improve the prognosis of lung cancer patients with wild-type EGFR are essential." (PMID 35721193, 2022). "For example, epidermal growth factor receptor (EGFR)-tyrosine kinase inhibitors (TKIs) and anaplastic lymphoma kinase (ALK)/c-ros oncogene 1 (ROS1) inhibitors have replaced chemotherapy as the first-line treatment of lung cancer." (PMID 36559280, 2022). "HB-EGF cleavage by matrix metalloproteinase 14 may enhance the EGFR signaling pathway to increase cancer cell growth in NSCLC and promotes lung cancer cell proliferation through the signal transducer and activator of transcription 3 (STAT3) signaling pathway." (PMID 36439487, 2022). "Our data suggest that NK1R plays an important role in lung cancer development through EGFR signaling and the crosstalk between NK1R and EGFR may provide a potential therapeutic target for lung cancer treatment." (PMID 35013118, 2022). "Surprisingly, CXCL10 increased in EGFR-mutant lung cancer cell lines itself and did not decrease due to EGFR-TKI treatment." (PMID 36612121, 2022). "Of 5980 lung cancer patients with ARID1A and/or EGFR SVs, only 100 patients (1.7%) had both SVs." (PMID 36117191, 2022). "Abnormal genetic alterations, such as epidermal growth factor receptor (EGFR) and epidermal growth factor receptor 2 (HER2), are frequently described to participate in the development of lung cancer." (PMID 35463955, 2022). "Consistent with earlier reports, PD‐1 antibody singlet treatment showed no noticeable treatment effects on these EGFR mutant lung cancers." (PMID 34898004, 2022).
lung cancer (continued). "Twelve (18%) patients had KRAS mutation, two patients were EGFR mutation‐positive (3%), one patient had a BRAF mutation (2%) and no patient had lung cancer that was ALK mutation‐positive." (PMID 34196124, 2022). "Heat shock protein 90 (Hsp90) has been implicated in the assembly of multiple chaperone complexes, regulating the stability and function of client proteins such as wild type c-RAF, mutant BRAF, mutant EGFR, as well as the EML4-ALK fusion protein in lung cancer." (PMID 35326726, 2022). "Therefore, this study suggests that personalized medicine should be included in the treatment protocol for lung cancer patients according to the status of HPV oncoproteins and EGFR expression." (PMID 36358752, 2022). "In both phase I and phase II lung cancer studies, patients treated with a combination of EGFR and MET inhibitors had substantial toxicity and no improvement in overall survival compared to single agents." (PMID 35325006, 2022). "Moreover, silencing of C-FLIP had sensitized EGFR-mutant NSCLC to erlotinib and, conversely, its overexpression rescued EGFR-mutant lung cancer cells from erlotinib treatment, presumably through modulation of NF-κB activity." (PMID 35463360, 2022). "We compared PFS and OS according to EGFR and EML in patients with lung cancer." (PMID 35948652, 2022). "Previous studies have revealed that E2 treatment induces rapid activation of the EGFR pathway, implying that nonnuclear ER regulates the EGFR pathway to influence lung cancer progression." (PMID 35034634, 2022). "One of the included trials randomized 139 non-diabetic lung cancer patients between epidermal growth factor receptor (EGFR)–tyrosine kinase inhibitors and the addition of metformin." (PMID 35337110, 2022). "A previous study indicated that treatment of Capmatinib over a period (e.g., 24 h) led to a dose-dependent increase of HER3 protein even though Capamtinib had the ability to suppress phosphorylation of EGFR and HER3 effectively in MET amplified H1993 lung cancer cells." (PMID 34974522, 2022). "Previous studies have revealed that E2 treatment induces rapid activation of the EGFR pathway, suggesting that nonnuclear ER translocation regulates the EGFR pathway to influence lung cancer progression." (PMID 35589688, 2022). "Human epidermal growth factor receptor 2 (HER2) belongs to the epidermal growth factor receptor (EGFR) family, and its overexpression/amplification has been confirmed in various malignant neoplasms, such as breast cancer (BC), prostate cancer, and lung cancer." (PMID 36175985, 2022). "IGF1R activity is related to EGFR-TKI resistance in NSCLC cell lines and lung cancer patients." (PMID 35264191, 2022). "However, our findings therefore suggest the pro-apoptotic switch in the role of EGFR and YAP1 during lung cancer metastasis." (PMID 35655775, 2022). "Recurrent EGFR fusions included CCT6A-EGFR fusions in two cases of lung cancer (2/13, 15.4%) and intergenic EGFR-SEC61G fusions, occurring at intergenic regions downstream of SEC61G, in three cases of gastric cancers and one case of lung cancer." (PMID 36369474, 2022). "More importantly, Carfilzomib synergized with PD‐1 antibody to shrink lung cancers driven by mutant EGFR, which is otherwise not responsive to PD‐1 antibodies." (PMID 34898004, 2022). "CXCL10 was the only chemokine that did not decrease after TKI treatment in EGFR-TKI-sensitive EGFR-mutant lung cancer cell lines during coculture with activated PBMCs." (PMID 36612121, 2022). "In regard to circRNAs, C190 sponges miR-142-5p to promote EGFR/MAPK/ERK signaling, which may contribute to EGFR TKI resistance in lung cancer patients." (PMID 36139582, 2022).